EN1 (engrailed homeobox 1)
Description:
Required for proper formation of the apical ectodermal ridge and correct dorsal-ventral patterning in the limb.
Synonyms: ENDOVESLB
Tractability: No criterion of Open Targets' tractability assessment is met for any kind of drug.
Gene: Protein-coding gene on chromosome 2 (118,842,171 to 118,847,648, reverse strand). Ensembl gene ENSG00000163064.
Subcellular location: Nucleus
Subcellular location (Human Protein Atlas): Nucleoli rim; Nucleoplasm
Gene Ontology:
Molecular function: DNA-binding transcription repressor activity, RNA polymerase II-specific; RNA polymerase II cis-regulatory region sequence-specific DNA binding; sequence-specific double-stranded DNA binding; DNA-binding transcription factor activity, RNA polymerase II-specific; DNA binding
Biological process: negative regulation of transcription by RNA polymerase II; anatomical structure morphogenesis; dopaminergic neuron differentiation; neuron differentiation; regulation of transcription by RNA polymerase II; skeletal system development; adult locomotory behavior; cerebellum development; drinking behavior; embryonic brain development; motor learning; negative regulation of neuron apoptotic process; regulation of DNA-templated transcription; response to cocaine; social behavior
Cellular component: nucleoplasm; nucleus; chromatin
Genetic constraint (gnomAD): Loss-of-function variants: 6 observed, 16.35 expected, observed/expected ratio (o/e) 0.37, 90% interval 0.2 to 0.72. The synonymous counts are far from expectation, so gnomAD's model fits this gene poorly and the ratio says little. Missense variants: 442 observed, 408.05 expected, observed/expected ratio (o/e) 1.08, 90% interval 1 to 1.17. Synonymous variants: 241 observed, 178.85 expected, observed/expected ratio (o/e) 1.35, 90% interval 1.21 to 1.5.
Homologues: Orthologues: chimpanzee EN1 (99% identical), macaque EN1 (98% identical), pig EN1 (94% identical), rat En1 (94% identical), mouse En1 (94% identical), dog EN1 (91% identical), rabbit EN1 (67% identical), guinea pig EN1 (65% identical), zebrafish en1b (46% identical), tropical clawed frog en1 (43% identical), zebrafish en1a (37% identical), Drosophila melanogaster en (33% identical), and 2 more. Paralogues in human: EN2 (40% identical), CPHXL (9% identical), CPHXL2 (8% identical).
Diseases named in the same sentence as EN1 in open-access papers:
EN1 is named in the same sentence as 75 diseases in open-access papers, as found by Europe PMC text mining. Sharing a sentence is not in itself a finding about the gene and the disease. The quoted sentences say what the papers report.
breast carcinoma (26 papers, 2015 to 2025). "We further evaluated the associations between predicted gene expression and risk of breast cancer by subtypes and identified two genes, EN1 and LINC01956 (for ER-negative and TNBC), showing an association at the Bonferroni-corrected significance level." (PMID 38697998, 2024). "We identified four new genes (CTD-3080P12.3, EN1, LINC01956, and NUP210L) showing a significant association with breast cancer risk at the Bonferroni-corrected significance level." (PMID 38697998, 2024). "Moreover, EN1-iPeps have been found to inhibit EN1’s role in activating intrinsic inflammatory pathways associated with tumor survival, which is particularly relevant in basal breast cancer, a subtype of breast cancer known for its aggressive behavior and poor prognosis." (PMID 39795861, 2024). "Reduced expression of EN1 induces caspase-3-dependent apoptosis, which can reverse the drug resistance of basal-like breast cancer cells." (PMID 37284316, 2023). "For example, the overexpression of homologous nuclear transcription factor Engrailed 1 (EN1) can lead to the resistance of basal-like breast cancer to the chemotherapeutic drug docetaxel." (PMID 37284316, 2023). "EN1 has been reported as a key regulator that contributes to the progression of a variety of human cancers, including breast cancer and salivary gland adenoid cystic carcinoma." (PMID 35163043, 2022). "Consistent with analysis of the four breast cancer microarray datasets, basal-like breast tumours had significantly greater EN1 expression variability (p = 3.7 × 10−146)." (PMID 34287743, 2021). "EN1 has been observed to be overexpressed in triple-negative breast cancers and basal-like breast cancers." (PMID 34287743, 2021). "Overexpression of EN1 has been observed to behave as a pro-survival transcription factor in basal-like breast cancer." (PMID 33135722, 2020). "We found that methylation of the BLAT1 CpG site, cg18250846, is significantly correlated with the methylation status at three sites in the EN1 promoter (cg20248516, cg22030072, and cg17167253) in breast cancer (p < 0.0001)." (PMID 30349062, 2018). "EN1 is over-expressed in basal-like breast cancer, and achieved significant differential expression between basal and other breast cancers in both UBCS (log2FC = 4.03, p = 2.26E-22) and TCGA (log2FC = 3.01, p = 8.04E-71) datasets." (PMID 27685983, 2016). "EN1 is highly expressed in breast cancer (BRAC), and ESR1 can increase eRNA transcription in BRAC." (PMID 36217201, 2022). "The use of peptides to interfere with the interactions of proteins involved in cancer has been demonstrated successfully with iPeps comprising a conserved hexamotif and the N-terminus flanking sequence of the homeobox of the transcription factor Engrailed 1 (EN1) in basal-like breast cancer." (PMID 34502261, 2021). "Our group first reported that EN1 is selectively overexpressed in basal-like breast cancers." (PMID 31636382, 2020). "EN1 CpG island is frequently hypermethylated in both colorectal and breast cancer." (PMID 26113876, 2015). "Importantly, the only regions that displayed a positive correlation between methylation and expression among the breast cancers in the TCGA database were four far-upstream or intragenic regions for the genes EN1, PITX2, APC and LHX2." (PMID 26510686, 2015). "Interestingly, En1 is also overexpressed in aggressive forms of breast cancer." (PMID 34658803, 2021). "Similar to EN1, we and others have described iPeps selectively inhibiting oncogenic TFs such as c-MYC in breast carcinoma models." (PMID 34502261, 2021). "It has been also reported that Stratifin (SFN) is methylated in 96% of breast cancer patients, whereas Homeobox A9 (HOXA9) and Engrailed homeobox 1 (EN1) are methylated in 95% and 80% of serum patients with ovarian tumor, respectively." (PMID 31443448, 2019).
breast carcinoma (continued). "Three genes (FOXC1, EN1, and ELF5) stood out by displaying a pattern opposite to that of FOXA1, with hypomethylation and expression in Basal tumors, but hypermethylation and repressed expression in all other breast cancer subtypes." (PMID 40155623, 2025). "At Bonferroni-corrected P < 0.05, we identified six genes associated with breast cancer risk, including four genes not previously reported (CTD-3080P12.3, EN1, LINC01956 and NUP210L)." (PMID 38697998, 2024). "Engrailed Homeobox 1 (EN1) was another upregulated gene that we identified, which is a protein-coding gene that helps control development and has been shown to affect bone metastases from breast cancer tumors." (PMID 39057065, 2024). "These three genes (CTD-3080P12.3, EN1, and LINC01956) have not been previously identified in TWAS for breast cancer risk." (PMID 38697998, 2024). "Several peptide variants were tested in this study (EN1-iPeps) which were capable of selectively reducing cell survival of basal-like breast cancer cell lines (EN1+) without affecting EN1− cells." (PMID 31636382, 2020). "Interestingly, reduced expression of EN1 in basal, but not luminal, breast cancer cell lines decreases viability, which can be partially rescued by overexpression of EN1." (PMID 34287743, 2021). "Unlike myoblasts and myotubes, the MCF-7 breast cancer cell line was hypermethylated not only in this region but throughout the body of the EN1 gene, which may explain why MCF-7 cells did not express EN1 while myoblasts and myotubes did." (PMID 26510686, 2015). "Nevertheless, when zooming out to the flanking regions, the profiles clearly show that hypermethylation affects many neighboring CpG islands in colon cancer but not in breast cancer, where hypermethylation is restricted to the EN1 CpG island (denoted by an arrowhead)." (PMID 26113876, 2015). "On the other hand, lots of TFs, like EN1, STAT3, SOX9, and FOXM1, showed essential oncogenic functions in non-luminal breast cancer." (PMID 34249704, 2021).
Parkinson disease (13 papers, 2009 to 2026). A progressive degenerative disorder of the central nervous system characterized by loss of dopamine producing neurons in the substantia nigra and the presence of Lewy bodies in the substantia nigra and locus coeruleus. "EN1 presence protects neurons from apoptotic insults, and EN1 downregulation causes dopaminergic neuronal degeneration, a hallmark of Parkinson’s disease." (PMID 35267409, 2022). "En1/2 and Nurr1 expression also prevents mitochondrial impairment, a well described pathogenic phenomenon in Parkinson’s disease, by inhibiting neurotoxic insult and the mitochondrial pathway of apoptosis, through regulation of the pro- and anti-apoptotic member of Bcl-2 family." (PMID 24685177, 2014). "Mesencephalic dopaminergic (mDA) neurons that innervate the striatum and degenerate in Parkinson’s disease (PD) express both EN1 and EN2." (PMID 38550565, 2024). "These neurons degenerate progressively in parkinsonian patients, in classical Parkinson’s disease animal models and in the En1-heterozygous mouse." (PMID 31451602, 2019). "mDA neurons from the Substantia Nigra (SN) and Ventral Tegmental Area (VTA) that die in Parkinson Disease (PD) express En1 and En2 in the adult and experience progressive mDA cell death in a En1+/- mouse line." (PMID 24396269, 2013). "In mice with loss of EN1, Parkinson disease-like motor or non-motor symptoms will appear, which implies that EN1 probably can be a therapeutic target for Parkinson disease." (PMID 31576231, 2019). "In heterozygote animals (En1+/-;En2-/-), which are viable and fertile, postnatal maintenance of the nigrostriatal dopaminergic system is afflicted, leading to a progressive degeneration specific to this subpopulation and Parkinson's disease-like molecular and behavioral deficits." (PMID 19291307, 2009). "In the GSE49036 dataset consisting of patients with Parkinson’s disease at different Braak stages, there was significant difference in the expression of EN1, PLOD3 and LOXL1 in the different Braak stages 0 to 6 of Parkinson’s disease." (PMID 36825022, 2023). "In the end, 2 NFRGs (EN1 and LOXL1) were identified as crucial for the development of Parkinson’s disease and the outcome of GBM." (PMID 36825022, 2023). "The similarities to the disease etiology in combination with the nigral phenotype of En1+/-;En2-/- mice suggests that haplotype variations in the Engrailed genes and/or P75NTR that alter their expression levels could, in part, determine susceptibility to Parkinson's disease." (PMID 19291307, 2009).
colorectal cancer (7 papers, 2009 to 2023). A primary or metastatic malignant neoplasm that affects the colon or rectum. "EN1 is hypermethylated in neoplasia, this alteration has been identified as a diagnostic marker in colorectal cancer." (PMID 27901495, 2017). "The elevated methylation frequencies of EN1 in colorectal adenomas and carcinomas lead us to evaluate its possible application as a diagnostic marker of colorectal cancer." (PMID 19384295, 2009). "Hypermethylation of EN1 has been reported in many cancers, including colorectal cancer, prostate cancer, and glioma, and the degree of methylation correlates with tumor grade and patient prognosis." (PMID 36825022, 2023). "EN1 plays a role in abnormal expression of EN1 is common in colorectal cancer, prostate cancer, and astrocytoma." (PMID 34992653, 2021). "EN1 is a transcription factor hypermethylated in multiple cancers, including colorectal cancer, prostate cancer and ovarian cancer, and has been considered as a potential biomarker for several tumours." (PMID 32649057, 2020). "To identify critical engrailed genes that contribute to the colorectal cancer tumorigenesis, we analyzed the mRNA expression of EN1 and EN2 in GSE9348, in which EN2 was significantly upregulated in CRC." (PMID 32732864, 2020). "This group of genes includes the homeobox gene En1, whose hypermethylation has been described as a promising biomarker of neoplastic stages of human colorectal cancer." (PMID 25933092, 2015). "We determined the methylation status of EN1 CpG island in the DNA obtained from stools, serum and the corresponding tumour samples in an independent series of 30 colorectal cancer patients." (PMID 19384295, 2009). "The three CpG islands associated with the promoter region of the genes EN1, SCTR and INHBB mapping to 2q14.2 have been identified earlier to be hypermethylated in colorectal cancer." (PMID 19384295, 2009). "We conclude that epigenetic suppression along 2q14.2 is common to most colorectal cancers and the presence of a methylated EN1 CpG island in stool DNA might be used as biomarker of neoplastic disease." (PMID 19384295, 2009). "Different studies have pinpointed the parallelisms between mouse and human colorectal cancer at epigenetic level and many of the genes we have found hypermethylated in early stages of mouse tumorigenesis (i.e., Lgr5, Axin2 and En1) may have potential clinical applications in human cancer." (PMID 25933092, 2015).
triple-negative breast carcinoma (7 papers, 2018 to 2024). An invasive breast carcinoma which is negative for expression of estrogen receptor (ER), progesterone receptor (PR), and human epidermal growth factor receptor 2 (HER2). "A recent study reported that En1 shows a transcriptional dependency in triple negative breast cancer associated with brain metastasis." (PMID 35349708, 2022). "The evaluation of EN1 protein by immunohistochemistry has been perplexing, with Kim and colleagues previously describing EN1 protein expression as being associated with improved survival in triple-negative breast cancer, opposite to that of EN1 RNA." (PMID 34287743, 2021). "In patients with triple-negative breast cancer, EN1 upregulation was correlated with significantly shorter overall survival times and an increased risk of brain metastases." (PMID 38291456, 2024). "Moreover, EN1 may predict risk of brain metastasis in patients with triple-negative breast cancer." (PMID 32612655, 2020). "The interference peptides (EN1-iPeps) that selectively inhibit EN1 activity can be used for the treatment of aggressive basal-like triple negative breast carcinomas (Gandhi, Blancafort & Mancera, 2018)." (PMID 31576231, 2019). "Recently, interference peptides (EN1-iPeps) that selectively inhibit EN1 activity have offered a novel route for the treatment of aggressive basal-like triple negative breast carcinomas." (PMID 29854286, 2018). "Engrailed‐1 (EN1) is a critical homeodomain transcription factor (TF) required for neuronal survival, and EN1 expression has been shown to promote aggressive forms of triple negative breast cancer." (PMID 38110836, 2024). "Although little is known about the role of EN1 and EGR3 in GBM, previous work showed that EN1 is a hub gene and that its downregulation significantly reduced the viability of triple-negative breast cancer cell lines." (PMID 32612655, 2020).
glioma (6 papers, 2019 to 2023). A benign or malignant brain and spinal cord tumor that arises from glial cells (astrocytes, oligodendrocytes, ependymal cells). "Similar expression trends were detected in the datasets studied by Henry Ford Hospital, further indicating that increased EN1 expression is associated with higher glioma grade." (PMID 35163043, 2022). "The analyses demonstrated that EN1 knockdown caused ROS increase in glioma cells compared with scramble controls." (PMID 35163043, 2022). "Kaplan–Meier survival analysis was chosen to explore the association between EN1 expression and 5, 10 and 15-year OS in patients with glioma through data mining in R2 using data in GSE16011." (PMID 31576231, 2019). "In conclusion, our study indicates that EN1 is frequently elevated in glioma tissues and associated with poor prognosis, and it may, therefore, be a promising diagnostic and prognostic marker for glioma patients." (PMID 35163043, 2022). "EN3 has additionally been reported in glioma and secretory carcinomas, while EN1 has also been reported in AML." (PMID 37686522, 2023). "Our follow-up analyses ultimately indicate that EN1 is tumorigenic for gliomas, regulating the proliferation and growth of cancerous cells by modulating Hedgehog signaling activity." (PMID 35163043, 2022). "Mechanistically, we show that EN1 promotes glioma cell proliferation and migration, doing so at least partially through regulating Hedgehog pathway activity." (PMID 35163043, 2022). "To investigate the potential mechanisms of EN1 in the glioma cell line, we used RNA sequencing to assess glioma cells after knocking down EN1." (PMID 35163043, 2022). "RNA-seq results also revealed that alteration of TULP3 was common to all examined EN1 KD glioma cell lines." (PMID 35163043, 2022). "To evaluate the functions of EN1 in glioma cells, we first assessed EN1 expression in four glioma cell lines, and we found that U-118 MG, U251, and A172 had higher EN1 expression than did the U-87 MG cell line." (PMID 35163043, 2022). "EN1 controls glioma cell proliferation, colony formation, migration, and tumorigenic capacity in vivo." (PMID 35163043, 2022). "Through cross-species transcriptome studies, we found that Engrailed 1 (EN1) is highly expressed in serum-free cultured glioma cells as well as glioma tissues, and increased expression level predicts a worse prognosis." (PMID 35163043, 2022). "Here, through RNA-seq analysis and further validation, we found that part of the function of EN1 in glioma cells was achieved through regulating SHH pathway activity." (PMID 35163043, 2022). "Higher expression of EN1 in glioma correlated with shorter patient 5, 10 and 15-year OS according to R2 (p < 0.001)." (PMID 31576231, 2019). "Results from GSE16011 showed that: glioma, LGG and LGG with IDH1 mutation patients with high EN1 expressions had significantly shorter 5, 10, and 15-year overall survival time (OS) (p < 0.001)." (PMID 31576231, 2019). "R2 results showed that lower EN1 expression was significantly correlated with longer 5, 10 and 15-year OS in glioma and LGG patients in the GEO dataset." (PMID 31576231, 2019). "We next carried out functional recovery experiments to determine whether EN1 exerts its functions in glioma cells via the Hedgehog pathway." (PMID 35163043, 2022). "We chose two online databases to analyze EN1 expressions in glioma and LGG." (PMID 31576231, 2019). "By data analysis in GSE16011 and TCGA-LGG, the consistent results showed that EN1 might be an indicator of favorable OS in glioma, especially in LGG." (PMID 31576231, 2019). "The colony number of EN1 KD cell lines after radiotherapy was significantly lower than the scramble control cell lines, suggesting that EN1 might modulate the cellular radiation sensitivity of glioma cells." (PMID 35163043, 2022).